PARP1 (poly(ADP-ribose) polymerase 1)
Diseases named in the same sentence as PARP1 in open-access papers (continued):
Sharing a sentence is not in itself a finding about the gene and the disease.
tumor (continued). "Kim and colleagues tested a new in-vivo delivery vehicle for the disruption of Poly (ADP-ribose) polymerase-1 (PARP-1) expression by using tumor-derived EVs loaded with Cas9 and PARP-1 sgRNA-encoding plasmids." (PMID 31661862, 2019). "We demonstrate that the vascular changes induced by RAPTA-T are related, in part, to the inhibition of poly-(ADP-ribose) polymerase 1 (PARP-1) which is associated to tumor vascular stabilization." (PMID 29980753, 2018). "PARP1 is a nuclear enzyme implicated in DNA repair, tumour proliferation and mediation of androgen receptor-DNA interaction." (PMID 29606109, 2018). "Triptolide increased the expression of associated apoptotic proteins (cleaved PARP1, cleaved caspase-3, and cleaved caspase-9) in tumor tissues." (PMID 30111354, 2018). "Depletion of NOX1 and NOX4 partially rescued the growth inhibition of PARP1-deficient tumor xenografts." (PMID 29684820, 2018). "PARP1 inhibition by olaparib induces synthetic lethality in tumor cells deficient in homologous recombination, an essential DNA repair pathway." (PMID 29535829, 2018). "PARP1-positivity was significantly associated with sex of patients (P = 0.038), higher tumor stage (P = 0.024), higher histologic grade (P = 0.008), and the expression of γH2AX (P = 0.001), BRCA1 (P = 0.009), and BRCA2 (P = 0.001)." (PMID 29784019, 2018). "Previously it has been shown that interference with DNA repair caused by PARP-1 inhibitors can result in radiosensitization of tumor cells when given concurrently with radiation in vitro and in vivo." (PMID 29152107, 2017). "Recent bioinformatic analysis of TCGA datasets revealed that PARP1 expression is restricted to higher grade tumours, and partially caused by genomic gain." (PMID 28654422, 2017). "Clinical trials have indeed confirmed the effectiveness of PARP1-i as a single treatment against BRCA-deficient tumours." (PMID 28427225, 2017). "Considering that PARP-1 promoted apoptosis/necrosis during IR injury and high PARP-1 expression was associated with tumor malignant potential, we adopted the PARP-1 inhibitor PJ34 to explore its role in HCC recurrence after liver transplantation." (PMID 29179487, 2017). "In mouse models, the up-regulation of PARP-1 was closely related to the greater tumor burden and increased hepatic susceptibility to recurrence after IR injury." (PMID 29179487, 2017). "Correlation analysis showed that the expression of NDRG1 in HCCs was significantly associated with tumor size and differentiation, PARP1 with tumor size and stage (p < 0.05)." (PMID 26883192, 2016). "Supporting this, a previous study has demonstrated that PARP1/2 can be trapped into a specific DNA sites causing direct cytotoxicity, suggesting that PARP1 is essential in Olaparib-mediated tumor suppression." (PMID 26540566, 2015). "PARP-1 inhibitors can be used with radiotherapy or chemotherapy to enhance the susceptibility of tumor cells to the treatment." (PMID 26314963, 2015). "Combination treatment caused dramatic antitumor activity, enhanced PARP1-hyperactivation in tumor tissue, and improved survival of mice bearing MiaPaca2-derived xenografts, with 33% apparent cures." (PMID 26602448, 2015). "It is significant that a set of the most strongly associated proteins (p <0.01), DFFA, MAP2K1, E2F5, PARP1, predict for longer survival when decreased, which is as would be expected, as these proteins have tumour-promoting characteristics." (PMID 25177240, 2014). "A rationale for inhibiting tumor growth by PARP1 inhibitors is that PARP1 inhibition was demonstrated to cause synthetic lethality by the failure to repair ssDNA breaks." (PMID 23921685, 2013). "Given the enormous interest in this target, it is important to understand the underlying mechanisms by which PARP-1 and other PARPs function in tumor cell biology." (PMID 23785295, 2013). "Arising from this research, PARP1-targeting therapy is gaining acceptance as an important strategy to treat tumor cells with BRCA1 or BRCA2 deficiencies." (PMID 23762475, 2013).
tumor (continued). "Parp1, a chromatin-associated enzyme, is involved in regulation of numerous processes, including proliferation, recovery from DNA damage, and tumor transformation." (PMID 22737085, 2012). "Themajor tumor types observed in the present study, such as tumors in the uterus,mammary gland, lung, and liver have been reported in PARP-1 deficient mice inprevious studies using recombinant genetic mutants." (PMID 19415146, 2008). "Parthanatos, a distinct form of regulated cell death mediated by poly (ADP-ribose) polymerase-1 (PARP-1), has been implicated in tumor biology and therapeutic resistance; however, the role of parthanatos-associated genes (PRGs) in STAD remains largely unexplored." (PMID 41004487, 2025). "This series of dual‐target inhibitors may exhibit enhanced anti‐tumor effects by synergistically intervening in both PARP1 and ATR‐associated signaling pathways." (PMID 40521858, 2025). "Its dysregulation may lead to cell death via NAD+ depletion, potentially selecting for PARP-1-deficient clones with a growth advantage during tumour progression." (PMID 41294806, 2025). "Together, our observations suggest that ALKATI sensitizes HGSC cells to apoptosis (probably though an association with PARP1) but this may have a relatively minor impact on tumor progression." (PMID 40387841, 2025). "Furthermore, PARP inhibitors are a class of therapeutic agents that primarily target and inhibit PARP1/2 proteins, thereby inducing “synthetic lethality” in tumor cells harboring BRCA1/2 mutations or exhibiting HRD." (PMID 41361128, 2025). "Taken together, these findings that PARP1 can be UFMylated and that a human tumor-associated mutation in PARP1 (PARP1-F553L) compromises PARP1 UFMylation demonstrate that PARP1 UFMylation may be involved in tumorigenesis." (PMID 38657044, 2024). "Since PARP1 also participates in DNA damage repair, it has been hypothesized that loss of both DNA-PK and PARP1 induce synthetic lethality for tumor cells due to loss of multiple repair pathways." (PMID 38682589, 2024). "PARG depletion is associated with PARPi resistance in HRD tumours by restoring PARP1 signalling." (PMID 39796639, 2024). "Overexpression of PARP1 and other DNA damage repair proteins may aid in repairing DNA lesions caused by Top2 inhibitors, allowing tumor cells to withstand treatment involving Top2 inhibitors." (PMID 36678591, 2023). "Furthermore, CDEAH selectively inhibits PARP1-deficient xenograft tumor growth compared to isogenic PARP1-proficient tumors." (PMID 37554969, 2023). "The tumor susceptibility gene TSG101 interacts with PARP1 and is essential for PARP1 activation." (PMID 36909172, 2023). "In BRCA-mutated OC-PDXs, AZD5305 achieved greater tumor regressions and longer duration of response as well as a superior impairment of visceral metastasis and improved survival benefit compared with the first-generation dual PARP1/2 inhibitors." (PMID 36994441, 2023). "Selective inhibition of PARP1 with antiproliferative activity against HR‐deficient tumor cells." (PMID 37808268, 2023). "The synthetic lethal interaction may be attributed to the HR deficiency caused by BRCA1/2 mutations, which in turn further impairs DNA repair through PARP1 inhibition, consequently killing tumor cells through a dual effect." (PMID 36230796, 2022). "Inhibition of efficient PARP1/2-dependent DDR is fatal for tumor cells with homologous recombination deficiencies (HRD), especially defects in breast cancer type 1 susceptibility protein 1 or 2 (BRCA1/2)-dependent pathway, while allowing healthy cells to survive." (PMID 36533080, 2022).
tumor (continued). "In clinical oncology, apart from selective targeting of HR-deficient tumour cells, PARP-1 inhibitors represent a promising tool to modulate the size of the mitochondrial population, thereby eliminating the enormous plasticity this organelle provides for tumour cells." (PMID 35887244, 2022). "The enhancement of PARP1 expression and activity can effectively repair the DNA damage caused by platinum drugs, leading to a decrease in the efficacy of chemotherapy on tumor cells." (PMID 35875162, 2022). "A potential cause of decreased PARP1 serum expression could be a result of tumor reduction upon treatment, which needs to be further investigated." (PMID 34319003, 2022). "Interestingly, larger injected masses (4.0 and 8.0 μg) also resulted in lower uptake of [18F]olaparib in the tumour plausibly caused by self-blocking, although the average PARP1 levels in all tissues are usually relatively high." (PMID 36210377, 2022). "High PARP1 expression was also associated with the invasiveness of tumor cells." (PMID 33572647, 2021). "In fact, a faulty DNA repair could explain the greater number of apoptotic cells observed in Parp1-deficient tumours." (PMID 33050515, 2020). "On the other hand, PARP-1-deficiency seems to bias T cell responses to a Th1 phenotype that may also impact tumor progression." (PMID 32046278, 2020). "Our study suggests that the concomitant reduction of NAMPT and PARP-1 activities in CDA-deficient tumor cells may be associated with a better prognosis." (PMID 32807821, 2020). "Besides, the volumes of tumours in the Parp1+/+ cohort were significantly bigger than those deficient of Parp1." (PMID 33050515, 2020). "Thus, PARP-1 causes different effects on the regulation of ROS in both normal and tumor cells after irradiation." (PMID 32862153, 2020). "Interestingly, comparative Sanger analysis of the DNA from blood and tumor DNA at the positions of rs7587470101 in TGFB2, and rs139924814 and rs3219143 in PARP1, revealed an over‐representation of the paternally inherited allele in the tumor." (PMID 30680959, 2019). "PARP1 functions as an antiviral protein in a preintegration step of avian retrovirus infection, hepatitis B virus transcription, and lytic replication of tumor-associated gammaherpesviruses EBV and KSHV." (PMID 31015836, 2019). "Furthermore, loss of PARP-1 has been reported to decrease tumor development in vivo in several mouse models." (PMID 31877876, 2019). "Consistent with this, PARP1-deficient mice challenged with alkylating drugs show high levels of DNA strand breaks compared with control animals, thus, confirming that PARP1 works as a caretaker tumour suppressor gene." (PMID 30991935, 2019). "RAPTA-T-dependent PARP-1 inhibition was indeed associated with a drop in tumor cell-derived VEGF." (PMID 29980753, 2018). "The tumor presented a susceptibility to a combined chemotherapy and the PARP1-inhibitor olaparib." (PMID 29855275, 2018). "The use of radiolabeled PARP‐1 inhibitors may be associated with two other complications: (i) Such probes may bind not only to dying tumor cells but also to immune cells, and (ii) DNA damage and repair will not always lead to cell death." (PMID 29528513, 2018). "A PARP1 mutation observed in a tumour from a PARPi-resistant patient prevents PARP1 trapping, suggesting that PARP1 mutations that impair trapping could contribute to clinical PARPi resistance." (PMID 29748565, 2018). "Therefore, our data would argue for the development of PARP1-specific inhibitors with a view to increasing efficacy of these agents in therapies that target HR-deficient tumours." (PMID 28973445, 2017). "CDK12 loss in a tumor could serve as another marker for treatment with PARP1/2 inhibitors or additional inhibitors of DDR network, as well as with other DNA-damaging compounds." (PMID 29090014, 2017).
tumor (continued). "PARP-1 inhibitors are now FDA-approved for advanced hereditary BRCA-mutated ovarian cancers given their ability to kill homologous recombination repair (HRR)-deficient tumour cells by synthetic lethality." (PMID 29152107, 2017). "So we hypothesized that the effects of PARP1 on NSCLC tumor migration may be associated with the PI3K-AKT pathway." (PMID 29152079, 2017). "A variety of tumor tissues have shown elevated expression of PARP1 protein, which may associate with deterioration, metastasis, and angiogenesis in tumors." (PMID 28991194, 2017). "High PARP1 expression was associated with larger tumor size and poorer survival." (PMID 26883192, 2016). "PARP-1 high-expression level was significantly associated with age, gender, and tumor stage." (PMID 27746584, 2016). "PARP-1 deficiency or inhibition can have a beneficial outcome in tumor treatment." (PMID 26314963, 2015). "Caspase-3 cleavage and PARP-1 activation demonstrate that siRNA RET/PTC3 might cause DNA damage which activates the cell death machinery for the destruction of tumour cells." (PMID 24759995, 2014). "PARP-1 overexpression was significantly associated with tumor grade." (PMID 24392019, 2013). "Our current study identifies PARP-1 as a pivotal modulator of the molecular and functional changes characteristic of EndoMT (involved in the loss of function of tumor-associated vessels) and of the phenotypic switch that facilitates the acquisition of pro-metastatic capacities by tumor cells." (PMID 23785295, 2013). "ROS induced by Bezielle cause extensive DNA damage and hyper activation of PARP-1 in tumor cells." (PMID 22319564, 2012). "PARP1 expression is strongly increased in many different tumor types compared with healthy adult tissue for a number of reasons, including the high mutational burden and genomic instability of tumor cells and their increased proliferative activity and DNA content." (PMID 38383387, 2024). "Moreover, the high PARP1 level was associated with increased invasiveness of tumor cells." (PMID 33572647, 2021). "In addition, an acquired low level of expression of PARP1 may be a cause of resistance to PARPi in patient-derived tumor xenograft models." (PMID 32316968, 2020). "Moreover, a defect in the ability of dually PARP-1/PARP-2-deficient T cells to differentiate into effector cells could have consequences for the anti-tumor response." (PMID 32046278, 2020). "This heterogeneity allowed us to test cells with different intrinsic sensitivity to trabectedin, in order to explore if trabectedin could efficiently activate PARP1, and if PARP1-specific inhibition could be exploited sufficiently to cause irreversible DNA damage, and eventually tumor cell death." (PMID 28454547, 2017). "However, tumours proficient in HR repair may also be susceptible to treatment with PARP-1 inhibitors if administered in combination with cytotoxic drug therapy and radiotherapy." (PMID 27515310, 2016). "Furthermore, our results suggest the possibility that tumour-specific mutation or inhibition of PARP1 could result in clinical PARP inhibitor resistance and disease progression." (PMID 23634208, 2013). "Previous studies have demonstrated that inhibition of indoleamine 2,3-dioxygenase (IDO) can enhance the sensitivity of human tumor cells to PARP1/2 inhibitors." (PMID 41900138, 2026). "Niraparib is a selective inhibitor of poly (ADP-ribose) polymerases 1 and 2 (PARP-1/2) that specifically targets tumor cells by preventing the repair of DNA damage induced by cytostatic agents." (PMID 41493488, 2026). "Parthanatos, a poly (ADP-ribose) polymerase-1 (PARP1)-dependent form of regulated cell death, has been implicated in tumor biology, yet its relevance in COAD remains poorly understood." (PMID 42029110, 2026).
tumor (continued). "One plausible explanation is that both PARP1 and PSMA are independently associated with aggressive tumor phenotypes and advanced stages of disease." (PMID 40682676, 2026). "Given the convergence of in vitro and in vivo evidence substantiating the involvement of p-Y158 PARP1 in PARPi resistance, we undertook the development of a monoclonal antibody against p-Y158 PARP1 for use in tumor immunohistochemistry (IHC) staining." (PMID 40460005, 2025). "Preclinical evidence suggests that PARP1 inhibition mediates the tumor-targeted effects of PARP inhibitors, while PARP2 inhibition is primarily responsible for myelosuppression." (PMID 41145467, 2025). "Here, MAEA was found for the first time to promote PARP1 ubiquitination and degradation, in turn suppressing tumor cell proliferation and chemoresistance." (PMID 39990651, 2025). "Poly (ADP ribose) polymerase 1 (PARP1) plays a central role in the response of DNA damage induced by tumor radiotherapy." (PMID 41367875, 2025). "One of the promising antiproliferative G-quadruplexes is bi-(AID-1-T), whose target protein in tumor cells is the cytoplasmic form of PARP1." (PMID 41304780, 2025). "DNA damage induced by chemotherapy leads to the activation of PARP1, thereby triggering DNA repair 11, ultimately enabling tumor cells to survive and thereby contributing to chemoresistance." (PMID 39990651, 2025). "This effort culminated in the successful detection of p-Y158 PARP1 in tumor tissues from TNBC patients." (PMID 40460005, 2025). "Toll-like receptor 9 (TLR9), another key player in immune evasion, upregulates PD-L1 and promotes tumor growth through the PARP1/STAT3 pathway, enhancing tumor cell proliferation, migration, and invasion." (PMID 40486875, 2025). "IHC analyses in PDX tumor tissues exhibited elevated p-Y158 PARP1 levels in talazoparib-resistant tumors." (PMID 40460005, 2025). "Its principle lies in directly assessing tumor cells’ reliance on the PARP1-EJ pathway - an alternative repair mechanism - when confronting DNA damage induced by radiotherapy combined with PARP inhibition." (PMID 41367875, 2025). "The utilization of PARP-1-targeting probes to detect PARP-1 expression in tumor cells has potential value for identifying patient populations suitable for PARPi-targeted therapy and improving treatment efficacy." (PMID 40444043, 2025). "The nuclear enzyme PARP-1 has recently attracted significant interest due to its critical role in tumor progression involving repair of oxidative DNA damage." (PMID 40518539, 2025). "The results demonstrated that PARP1 expression increased upon MRPL21 overexpression and decreased upon MRPL21 knockdown, suggesting that MRPL21 regulates tumor progression by binding to PARP1 and modulating its expression." (PMID 40713706, 2025). "MRPL21 affected the mitochondrial OXPHOS process and modulated tumor cell proliferation, metastasis, and autophagy via PARP1 activity and the downstream PI3K/AKT/mTOR signaling pathway, thereby contributing to chemoresistance of HNSCC." (PMID 40713706, 2025). "IHC staining of PARP1 in xenograft tumor tissues showed consistent results, indicating that sesamin treatment activated PARP1 levels both in vitro and in vivo." (PMID 40303286, 2025). "An alternative topical marker is PARPi‐FL, which highlights the overexpression of poly‐ADP ribose polymerase 1 (PARP1) in tumours." (PMID 39629534, 2025). "p97 inhibitors can also prolong PARP1 trapping to enhance PARP inhibitor-induced cytotoxicity in homologous recombination-defective tumor cells." (PMID 41008789, 2025). "In vivo experiments also confirmed that repression of the PCNA/PARP1 axis significantly reduced HCC tumor growth." (PMID 40313621, 2025). "MRPL21 promotes tumor proliferation and metastasis by regulating PARP1 expression, and knockdown of PARP1 reverses the oncogenic effects of MRPL21." (PMID 40713706, 2025).